LINC00930 (long independently transcribed non-coding RNA 930)
Gene: Long non-coding RNA gene on chromosome 15 (92,567,817 to 92,574,529, reverse strand). Ensembl gene ENSG00000258647.
Diseases named in the same sentence as LINC00930 in open-access papers:
LINC00930 is named in the same sentence as 3 diseases in open-access papers, as found by Europe PMC text mining. Sharing a sentence is not in itself a finding about the gene and the disease. The quoted sentences say what the papers report.
nasopharyngeal carcinoma (3 papers, 2022 to 2024). A carcinoma arising from the nasopharyngeal epithelium. "We are actively pursuing a clinical strategy to treat nasopharyngeal carcinoma by interfering with LINC00930 and the target gene PFKFB3." (PMID 35209949, 2022). "LINC00930 was first reported in nasopharyngeal carcinoma, where it binds the RBBP5 and GCN5 complexes to the PFKFB3 promoter, elevates H3K4 trimethylation and H3K9 acetylation levels, transactivating PFKFB3, thereby promoting glycolytic flux and cell cycle progression." (PMID 38789960, 2024). "LINC00930, which was first reported in 2022 to be strongly up-regulated in the nasopharyngeal carcinoma(NPC), positively correlated with tumor stage and grade and associated with lymphatic invasion, metastasis, and poor prognosis." (PMID 38789960, 2024). "For example, LINC00930, an oncogenic lncRNA in nasopharyngeal carcinoma, promoted PFKFB3‐mediated glycolysis and histone modification, and targeting LINC00930 and PFKFB3 may be an effective approach to enhance radiosensitivity in patients with nasopharyngeal carcinoma." (PMID 35924724, 2023).
cancer (2 papers, 2022 to 2024). A tumor composed of atypical neoplastic, often pleomorphic cells that invade other tissues. "First, normalized expression level of LINC00930 was significantly increased in cancer tissues compared to adjacent non-tumor tissues from the TCGA HNSC dataset." (PMID 35209949, 2022).
tumor (2 papers, 2022 to 2024). "High LINC00930 expression levels were associated with tumor diameter in PC tissues, lymphatic metastasis and TNM stage." (PMID 38789960, 2024). "Herein, we found that the expression of LINC00930 was significantly down-regulated in PC cell lines and tissues, and associated with tumor size, lymphatic metastasis, TNM stage and poor prognosis." (PMID 38789960, 2024). "Here, we found that the expression of LINC00930 was down-regulated in PC tissues, which was closely related to clinicopathological features, including tumor size, lymphatic metastasis, TNM stage and poor prognosis." (PMID 38789960, 2024). "Our findings indicated that LINC00930 was a mediator of tumor malignancy, highlighting the potential of LINC00930 as a therapeutic approach in PC." (PMID 38789960, 2024). "Collectively, our findings establish a novel mechanism of lncRNA regulating tumor metabolism, of which LINC00930 regulates the key glycolytic gene PFKFB3 by epigenetic modification." (PMID 35209949, 2022). "Consistently, treatment with PFK15 for 24 h indeed weakened the oncogenic effect induced by the LINC00930, including cell proliferation, tumor glycolysis, F-2,6-BP and lactate levels." (PMID 35209949, 2022). "Knockdown of LINC00930 significantly suppressed tumor growth, while LINC00930 overexpression promoted tumor growth, as demonstrated by the xenograft tumor growth curve." (PMID 35209949, 2022). "Furthermore, targeting LINC00930 during radiotherapy accelerates tumor shrinkage." (PMID 38789960, 2024). "Clinically, targeting LINC00930 and PFKFB3 in combination with radiotherapy induced tumor regression." (PMID 35209949, 2022). "In this study, we demonstrated that LINC00930 epigenetically upregulated PFKFB3 and activating glycolysis process and cell cycle progression at the G1/S phase transition, thus regulating NPC cell proliferation and tumor growth." (PMID 35209949, 2022). "We hypothesized that LINC00930 and PFKFB3 depletion in combination with radiotherapy might have a better anti-tumor effect." (PMID 35209949, 2022). "Furthermore, targeting LINC00930 and PFKFB3 during radiotherapy accelerates tumor shrinkage." (PMID 38789960, 2024).